IL10 (interleukin 10)
Diseases named in the same sentence as IL10 in open-access papers (continued):
Sharing a sentence is not in itself a finding about the gene and the disease.
Sepsis (continued). "A cytokine array found that the QX1 formula attenuated sepsis-induced upregulated levels of serum IFN-γ, IL-1β, IL-3, IL-6, IL-17, IL-4, IL-10, and TNF-α." (PMID 32908632, 2020). "In the present study, our findings indicated that rats with sepsis showed higher levels of d‐lactic acid, FD‐40, MDA, DAO, IL‐10 and IL‐6, compared with the sham group, but the SOD activity was decreased in sepsis rats." (PMID 32383354, 2020). "By 24 h after the operation, the Sepsis-G group exhibited higher tumor necrosis factor (TNF)-α, IL-6, and IL-10 gene expressions than the sham group and higher TNF-α and IL-6 expressions than those of the Sepsis-C group." (PMID 32295272, 2020). "It was suggested that the serum levels of IL-6, IL-8, and TNF-α were significantly higher whereas those of IL-10, IL-13, and TGF-β were significantly lower in the sepsis group than those in the sham group." (PMID 31830649, 2020). "While IL-2, CXCL10, and TNF-α contribute to the pathogenesis of sepsis, IL-7, IL-10, GCSF, MCP1, M1P1A are likely elevated as an endogenous attempt to combat sepsis." (PMID 32973504, 2020). "P2Y12 receptor-deficient mice also showed diminished production of inflammatory mediators (i.e., IL-6, TNF-α, IL-10, and MIP-1) and reduced sepsis-induced lung injury." (PMID 33519492, 2020). "We then examined the serum levels of inflammatory cytokine TNF-α, IL-6, IL-1β, and IL-10, and the clinical markers of acute systemic inflammation MCP-1 and CRP by ELISA in LPS-induced sepsis model." (PMID 32457606, 2020). "In MRSA-induced sepsis mouse model, XBJ decreased the secretion of IL-6, TNF-α, MCP-1, MIP-2, and IL-10 in sera and alleviated lung, liver, and kidney damage." (PMID 32153410, 2020). "We have recently shown that numbers of IL-10 producing B lymphocytes and MDSC remain increased for months after sepsis." (PMID 30730978, 2019). "Overall, our study shows that there is an “immunoparalysis” in severe leptospirosis and sepsis: low quantity of NK and TCD4+ cells, low expression of IFN-γ, IL-12, IL-6, IL-1 and IL-2 and high expression of IL-10." (PMID 31114579, 2019). "Inhibition of calcium/calmodulin-dependent protein kinase Iα increased survival rate by reducing systemic concentrations of IL-10, IL-6, TNF-α, and HMGB1 in a CLP model of sepsis." (PMID 30848296, 2019). "Levels of plasma IFN-γ, IL-4 and IL-10 in blood serum collected upon enrolment in healthy control, ICU control and severe sepsis patients were measured." (PMID 30813927, 2019). "However, in foals evidence suggests that IL-6 protein is lower in the blood of septic vs. healthy foals and that the IL6:IL10 ratio, which was higher in the healthy age matched foals compared to septic foals, may be a useful prognostic indicator for neonatal septicemia." (PMID 30931316, 2019). "Our data would also be compatible with immune suppression by IL-10 producing B cells and MDSC which are still increased in numbers 30 days after sepsis." (PMID 30730978, 2019). "Regression analyses demonstrated significant, inverse correlations between IL-6, IL-10, and MCP-1 levels and days after sepsis." (PMID 30300408, 2018). "The analysis of the signature of healthy PBMCs stimulated with cytokines, soluble PAMPs and bacteria, frequently involved in sepsis, showed that the spectra of PBMCs from septic patients matched with those of PBMCs stimulated by IFN-γ, IL-10 and CpG-ODN." (PMID 30064357, 2018). "Circulating levels of the cytokines IL-6, IL-8, IL-10, MCP-1, IP-10, and TNF were significantly increased in septic patient at all three time points (<12 hours, 4 days, and 14 days after sepsis) compared to healthy controls." (PMID 30300408, 2018). "Moreover, a major mechanism of sepsis immunosuppression is in liver desensitization, where the production of proinflammatory cytokines involves the concomitant induction of anti-inflammatory mediators, such as IL-10, in an attempt to protect the liver from injury." (PMID 30524657, 2018).
Sepsis (continued). "IL-35 levels were observed to display a positive correlation with the levels of other pro-inflammatory mediators released in sepsis (including; IL-6, IL-8, IL-27, TNF-α and IL-10)." (PMID 29641433, 2018). "The levels of IL-10 and PCT were significantly elevated in sepsis group, while all the 4 therapy groups effectively reduced the level." (PMID 30687281, 2018). "Our data show association between serum levels of the cytokines IL-4, IL-6, IL-10 and TNF, and cognitive performance of patients with severe sepsis or septic shock." (PMID 29540719, 2018). "We aimed to investigate if reductions in the plasma concentrations of TNF-α, interleukin (IL)-6 and IL-10, and of the IL-6 rate of change at 24 h after ICU admission were survival predictors for Vietnamese patients with sepsis and septic shock." (PMID 30400775, 2018). "Firstly, the current study found that sepsis rats exhibited increased expressions of D-lactic acid, DAO, bacterial translocation, MDA, TNF-α, IL-6, and IL-10, in addition to decreased SOD activity." (PMID 30340459, 2018). "Here, we demonstrate that omega-9 treatment is associated with increased levels of the anti-inflammatory cytokine IL-10 and decreased levels of the proinflammatory cytokines TNF-α and IL-1β in peritoneal lavage fluid of mice with sepsis." (PMID 30538802, 2018). "In the sepsis model with strain ATCC 17978, only IL-10 levels were significantly higher after 4 h of infection under hypoxia (P < 0.05)." (PMID 30082478, 2018). "CLP-sepsis in mice on HFD resulted in large increases in the serum levels of TNF-α, IL-6, KC, and IL-10 when compared to mice on HFD subjected to sham surgery and mice on chow diet subjected to CLP (P < 0.05)." (PMID 30619349, 2018). "Previous studies suggested that IL-10-mediated effects are time dependent as IL-10 neutralization at the time of a cecal ligation and puncture (CLP)-induced sepsis increased the sepsis-induced mortality." (PMID 30581430, 2018). "Cytokine changes have been extensively studied in patients with septicemia or after exposure to endotoxin with sequential increases in TNF-α, IL-1β, IL-6, IL-1Ra, and IL-10." (PMID 29149303, 2018). "Compared to the sepsis group, all the therapy groups showed significantly higher survival rates and with evident reductions in the WBC count, serum PCT, and serum IL-10." (PMID 30687281, 2018). "After sepsis, the frequency and numbers of IFN-γ-expressing DN T cells consistently remained higher than IL-10+ cells." (PMID 29466409, 2018). "The therapeutic effects of rSj-Cys treatment were associated with the significant reduction of pro-inflammatory cytokines (TNF-α, IL-1β and IL-6) and boost of IL-10 and TGF-β1 cytokines in sera of mice with sepsis." (PMID 28482922, 2017). "Our study is the first to demonstrate that GIK decreased the rate of mortality in a rat model of sepsis, decreased the production of intestinal tissue proinflammatory cytokines, including IL-1β, IL-6 and TNF-α, and increased the level of IL-10." (PMID 28428961, 2017). "As shown in this study cohort, the median IL10/TNF ratio was lowest among SIRS-N patients at 1.2 and increased progressively with increasing severity of sepsis to 4.5 among those with septic shock." (PMID 31058274, 2017). "We found that sepsis Arrb2 TG mice were immunosuppressive, characterized by reduced pro-inflammatory (TNF-α, INF-γ) and increased anti-inflammatory (IL-10, IL-4) cytokines expression." (PMID 28525390, 2017). "High expression of IL-10 and TNF-α correlate with poor prognostic in patients with severe sepsis whereas higher levels of TNF-α, IL-6, and soluble TNF receptor (sTNFR) are associated with early hemodynamic deterioration." (PMID 29269852, 2017). "The initially elevated IL10/TNF ratio normalized to <1 for both SIRS-N and SIRS-P (sepsis and severe sepsis) patients following 72 h of effective therapy while those with septic shock remained elevated at 1.9." (PMID 31058274, 2017).
Sepsis (continued). "The IL-10/TNF-α ratio, which is a marker of the balance between anti-inflammatory and hyper-inflammatory states in sepsis, was assessed." (PMID 28918754, 2017). "Induction of sepsis by CLP resulted in early 1.5–20-fold increases in IL-6, IL-10, IFNγ and TNFα over that induced by sham surgery." (PMID 28724977, 2017). "Clinical sepsis scores were monitored; serum cytokines (TNF-α, IL-6, IL-10) and chemokines (MIP-1α) were measured at the end." (PMID 28759625, 2017). "This study documents the endogenous production of IL-6, TNF-α and IL-10 in rats with cecal ligation and puncture (CLP) induced sepsis on conscious animals with intermittent blood sampling in the individual rat during a 72-h period." (PMID 29204105, 2017). "The study further supports the usefulness of IL-8, IL-6, IL-10, and PCT as biomarkers of sepsis in febrile neutropenic children." (PMID 28769538, 2017). "We detected higher serum levels of cytokines TNF-α (5.7 vs. 0.7 pg/ml, P < 0.001), IL-6 (24.8 vs. 3.8 pg/ml, P < 0.001), IL-10 (30.0 vs. 11.9 pg/ml, P = 0.040), and VEGF (177.9 vs. 48.1 pg/ml, P = 0.018) in sepsis sera." (PMID 28086962, 2017). "The rapid peaks in TNF-α and IL-10 are supported by data published for Wingate SIT and are more akin to the release pattern seen during sepsis." (PMID 27034919, 2016). "al., the cytokine secretions of TNF-α, IFN-γ, IL-6 and IL-10 were globally decreased after LPS and α-CD3/28 stimulation in patients who died from sepsis." (PMID 27056672, 2016). "PC2iNTS is characterized by a cytokine profile typically described in patients with sepsis, with concomitantly raised proinflammatory (IL-6, IL-8, CXCL10, and IL-15) and anti-inflammatory (IL-10 and IL-1Ra) cytokines." (PMID 27170644, 2016). "An analysis for severe sepsis/septic shock/SIRS in CAP/pneumococcal disease was available only for the SNPs IL6 rs1800795 and IL10 rs1800896 with both series providing significant results." (PMID 27725770, 2016). "IL-10, a negative regulator of inflammation, and CXCL-1, a chemokine involved in neutrophil migration, are also well-characterized serum markers of CLP sepsis severity." (PMID 26790027, 2016). "It is reported that CD1d blockade prior to sepsis had a positive impact on survival in experimental CLP, which correlated with a decrease in spleen NKT cells and in circulating IL-6 and IL-10." (PMID 26114123, 2015). "In 15 patients fulfilling the criteria for severe sepsis, we measured plasma-NGAL, plasma Crea and eGFR, CRP, leukocyte count as well as IL-6, IL-8 and IL-10." (PMID 25893429, 2015). "A recent study on sepsis patients compared plasma levels of TNF-α, IL-6 and IL-10 to immune-staining of freely circulating monocytes and leukocytes." (PMID 25958003, 2015). "In a sepsis model, CO-mediated activation of the MKK3/p38 MAPK signaling pathway was involved in the induction of IL-10." (PMID 26557739, 2015). "Based on a murine cecal puncture ligation model of sepsis, the authors suggested the observed reduction in mortality of septic mice after intravenous administration of MSC to be due to the IL10 release by PGE2 reprogrammed macrophages." (PMID 25562599, 2015). "To evaluate the neuroinflammation in the sepsis survivors, we measured TNF-α, IL-1β, IL-6, and IL-10 expressions in the PFC and hippocampus." (PMID 26416717, 2015). "In contrast to the patients with sepsis, patients with chronic rheumatism presented a significant lower elevation of inflammatory markers such as CRP, leukocyte count, IL-6 and IL-10 (P<0.05) reflecting the moderate inflammatory condition." (PMID 25893429, 2015). "Sepsis increased plasma levels of tumour necrosis factor alpha (TNF-α), interleukin 6 (IL-6) and IL-10." (PMID 25413250, 2014). "Blood samples were collected at the time that severe sepsis was diagnosed to determine serum levels of CCCK-18, tumor necrosis factor (TNF)-alpha, interleukin (IL)-6 and IL-10." (PMID 25290885, 2014).
Sepsis (continued). "The strengths of our study were the large sample size and the follow-up of circulating TIMP-1, MMP-9, TNF-alpha, IL-10, and PAI-1 levels throughout the first week after diagnosis of severe sepsis." (PMID 24727739, 2014). "In the present study we demonstrated that mice with disruption of Atg7 in T cells exhibited a reduced cytokine production of IL-2, IFN-γ, IL-4, IL-10 and IL-17 by CD4+ T cells after sepsis, compared to septic wild-type mice." (PMID 25029098, 2014). "In the sepsis group, the levels of TNF-α, IL-10 and NF-κB were significantly increased compared with those in the control group (P<0.05)." (PMID 25009602, 2014). "Apart from IFN-I, we also mentioned the overlapping roles of IL-10 and IFN-I in impairing CTL immunity of sepsis patients." (PMID 25144375, 2014). "It has been recently demonstrated that Nod2 mediates the production of IL-10, which enhances the production of C5a, contributing to an increased mortality rate after CLP-induced sepsis." (PMID 25084278, 2014). "Anti-inflammatory cytokines, such as IL-10 and TGF-β, are important inflammatory mediators, since they play a major role in preventing excess proinflammatory response during sepsis." (PMID 25614712, 2014). "Female patients with sepsis had a higher survival rate, which was correlated with lower TNF-α and higher IL-10 levels, while male trauma-patients showed higher IL-6 level than females." (PMID 24945834, 2014). "Levels of IL-6, IL-10 and TNF-α were predictive for fatal outcome in patients with sepsis, while IL-10 levels were predictive for survival." (PMID 23520553, 2013). "It was suggested that low miR-150 serum levels identify septic disease in these patients and that miR-150 levels correlate with classical prognosis scores such as SOFA or established markers for sepsis and inflammation such as TNF, IL-10 or IL-18." (PMID 23372743, 2013). "Unlike terminally differentiated macrophages and monocytes, these cells produce large amounts of IL-10 and TNF-alpha after sepsis or trauma." (PMID 24371374, 2013). "Nod2−/− mice showed lower levels of C5a, IL-10, and IL-1β in serum and peritoneum, but higher survival rate during CLP-induced sepsis compared to wild type mice." (PMID 23675299, 2013). "This cytokine gene expression index consisted of the difference in log mRNA copy numbers for cytokines that were decreased in sepsis, namely, IFNγ, TNFα, IL7, and IL23, and the cytokine increased in sepsis, namely, IL10 (IFNγ + TNFα + IL7 + IL23–IL10)." (PMID 23935244, 2013). "Therefore, the NOD2-mediated IL-1β-IL-10 regulatory loop in neutrophils helps enhancement of C5a generation, which may partially account for the different kinetics of pro- and anti-inflammatory cytokines in sepsis." (PMID 23675299, 2013). "In a multivariate nominal logistic regression model comparing gene expression in patients with infection and those with sepsis at ICU admission, IL10 (P = 0.02), IFNγ (P < 0.0001), and TNFα (P = 0.03) retained statistical significance." (PMID 23935244, 2013). "Taken together, these data suggest that NOD2-mediated IL-1β-dependent and/or IL-1β-independent IL-10 production enhances C5a generation by suppressing CD55 expression on neutrophils, thereby aggravating sepsis." (PMID 23675299, 2013). "An algorithm utilising mRNA copy number for TNFα, IFNγ, IL7, IL10, and IL23 accurately distinguished sepsis from severe sepsis with a receiver operator characteristic value of 0.88." (PMID 23935244, 2013). "The serum and peritoneal C5a levels were not altered by administration of rIL-1β to Il-10−/− mice, whereas injection of recombinant C5a reduced survival rates in Il-10−/− and Il-1r−/− mice during CLP-induced sepsis." (PMID 23675299, 2013). "Here, we demonstrate that NOD2 enhances C5a generation by IL-10-mediated suppression of CD55 expression on neutrophils, thereby aggravating polymicrobial sepsis." (PMID 23675299, 2013).
Sepsis (continued). "Anti-PD-L1 antibody administration prevented sepsis-induced depletion of lymphocytes, increased tumor necrosis factor (TNF)-α and interleukin (IL)-6 productions, decreased IL-10 production, and enhanced bacterial clearance." (PMID 24324295, 2013). "Hyporesponsiveness for LPS stimulation was seen in patients with severe sepsis compared to simple sepsis patients for IL6, IL8, IL10 and TNFα reaching significant results for TNFα." (PMID 23414215, 2013). "A number of inflammatory cytokines, including IL-6, IL-10, IL-1, and TNF-α were involved in sepsis, which contributes to tissue and organ damage." (PMID 24324295, 2013). "IL-6 is one of the first acute phase cytokines released in sepsis/endotoxemia and is followed by increases in the levels of IL-1β, IL-8, TNF-α and IL-10." (PMID 23078757, 2012). "As sepsis progresses, complement activation by considerable release of cytokines (TNF-α, IL-6, IL-10, etc.)produced enormous components, such as C3a, C4a, and C5a, and further consumed the pool of complement C3 and C4." (PMID 23091606, 2012). "In sepsis patients in our study, IFN-γ concentration correlated with the KT ratio only at baseline, whereas IL6 and IL10 correlated with the KT ratio both at baseline and longitudinally." (PMID 21731667, 2011). "In sepsis patients, the KT ratio correlated with plasma IFN-γ (rs = 0.44, p = 0.0002), IL6 (rs = 0.49, p<0.0001) and IL10 (rs = 0.62, p<0.0001)." (PMID 21731667, 2011). "In the presence of SIRS or sepsis, CRP, IL-6, IL-10, Prognostic Inflammatory and Nutritional Index (NI), and triglycerides—but not glucose, VO2, or VCO2 increased significantly." (PMID 20490277, 2010). "• Anti-PD-L1 antibody administration prevented sepsis-induced depletion of lymphocytes, increased TNF-α and IL-6 production, decreased IL-10 production, and enhanced bacterial clearance." (PMID 21118528, 2010). "Anti-PD-L1 antibody administration prevented sepsis-induced depletion of lymphocytes, increased tumor necrosis factor (TNF)-α and interleukin (IL)-6 production, decreased IL-10 production, and enhanced bacterial clearance." (PMID 21118528, 2010). "We next identified, in each cohort, genes that are well known in the sepsis literature (for example, tumour related factor (TNF), interleukin (IL)-1, IL-8, IL-10 and TGF-beta)." (PMID 21190579, 2010). "Previous studies of our group showed that induction of sepsis by cecal ligation and puncture (CLP) leads to a significant increase in the plasma levels of TNF-α, IL-6, and IL-10." (PMID 19594900, 2009). "As it is well known that IL-10 and TNF-alpha play an important role in immune response and are dysregulated in sepsis patients, we checked by using an additional target prediction program (RNA22) to identify possible regions of interaction with miR-150." (PMID 19823581, 2009). "In our study, the changes in the systemic levels of IL-6, IL-1-beta, IL-10, and CRP were unable to discriminate survivors from non survivors during the first week of severe sepsis." (PMID 19718443, 2009). "We have found that elevated IL-10 and decreased TNF in the first few hours of experimental sepsis is correlated with increased survival." (PMID 18937852, 2008). "Concentrations of IL-1β, IL-6, IL-7, IL-8, IL-10, IL-13, interferon-γ, MCP-1 and tumour necrosis factor-α were significantly higher in septic shock patients than in those with severe sepsis." (PMID 17448250, 2007). "Early sepsis disease 12 h post-infection was characterized by cytokine storm, with concentrations of IFN-γ, CCL2, IL-6, IL-17A, IL-1α, IL-10 and M-CSF significantly elevated in multiple tissues up to 7 days post-infection when mice had recovered from objective clinical measures of disease." (PMID 41910926, 2026). "Plasma interleukin-10 (IL-10) (0.0 pg/ml; IQR, 0.0-4.8 vs 28.8 pg/ml; IQR, 7.5-51.7; P = 0.003) and IL-15 (0.0 pg/ml; IQR, 0.0-0.0 vs 0.0 pg/ml; IQR, 0.0-5.6; P = 0.024) levels were significantly higher in the sepsis group." (PMID 41996420, 2026).